PKD1P6 (polycystin 1, transient receptor potential channel interacting pseudogene 6)
Synonyms: HG6
Gene: Transcribed unprocessed pseudogene on chromosome 16 (15,125,242 to 15,154,564, reverse strand). Ensembl gene ENSG00000250251.
Diseases named in the same sentence as PKD1P6 in open-access papers:
PKD1P6 is named in the same sentence as 2 diseases in open-access papers, as found by Europe PMC text mining. Sharing a sentence is not in itself a finding about the gene and the disease. The quoted sentences say what the papers report.
cancer (1 paper, 2021). A tumor composed of atypical neoplastic, often pleomorphic cells that invade other tissues. "The results of high-throughput sequencing showed that TRP ion channel-related genes, such as TRPC7-AS1, TRPC4AP, PKD1P6, and PKD1P1, were highly expressed in cancer tissues than those in paracancerous tissues." (PMID 34512754, 2021). "We also found that the expression of TRP ion channel-related genes such as TRPC7-AS1, TRPC4AP, PKD1P6, and PKD1P1 in cancer tissues was higher than those in adjacent tissues." (PMID 34512754, 2021).
PKD1P6 also shares sentences with these, for which no sentence is quoted: breast carcinoma (1 paper).